BRCA1 (BRCA1 DNA repair associated)
Diseases named in the same sentence as BRCA1 in open-access papers (continued):
Sharing a sentence is not in itself a finding about the gene and the disease.
ovarian carcinoma (continued). "In contrast, in spontaneous ovarian cancers FANCA mutations are rare, with both germline and somatic mutations in BRCA1/2 occurring far more frequently than any other FA genes." (PMID 36046263, 2020). "For tumors that harbor a known alteration in HRR genes, such as BRCA1 or BRCA2, higher tumor mutational burden and a greater number of tumor-infiltrating lymphocytes has been seen in breast and ovarian cancer." (PMID 32457830, 2020). "The breast and ovarian cancer-specific tumor suppressor BRCA1, along with its heterodimer partner BARD1, plays a critical role in DNA repair, drug resistance, centrosome regulation, and transcription." (PMID 32528278, 2020). "Approximately 5%‐10% and 20% of breast and ovarian cancer cases are considered hereditary tumors, but only 25% of HBOC are associated with BRCA1/2 pathogenic variants, which affect DNA repair mechanisms." (PMID 32812259, 2020). "As such, germline carriers of BRCA1 and BRCA2 are predisposed to develop breast and ovarian cancers that have a predictable genomic profile." (PMID 32403357, 2020). "The 5–10% of breast/ovarian cancers (BC and OC) are inherited, and germline pathogenic (P) variants in DNA damage repair (DDR) genes BRCA1 and BRCA2 explain only 10–20% of these cases." (PMID 32957588, 2020). "PARP inhibitors are effective in ovarian cancers with homologous recombination deficiency (HRD), 40% of which are attributed to BRCA1/BRCA2 germline or somatic variants." (PMID 32813918, 2020). "It is estimated that about 44% of women who inherit a deleterious BRCA1 mutation and about 17% of women who inherit a deleterious BRCA2 mutation will develop ovarian cancer by the age of 80." (PMID 32419845, 2020). "An assortment of mutations in the BRCA1 and BRCA2 genes have been shown to substantially increase the risk of breast and ovarian cancers." (PMID 32109416, 2020). "Women with a BRCA1 or BRCA2 mutation have high lifetime risks of developing breast and ovarian cancer." (PMID 33014209, 2020). "This study was set out to identify BRCA1/BRCA2 mutations in patients at high risk of familial breast and ovarian cancer using a systematic approach." (PMID 33067490, 2020). "Long non-coding RNAs (lncRNAs) have been reported to interact with BRCA1/2 to regulate homologous recombination (HR) by diverse mechanisms in ovarian cancers (OvCa)." (PMID 32850807, 2020). "In-vitro dosimetric analysis revealed that the relative biological effectiveness (RBE) of the Auger-emitting [125I]KX1 in comparison to low-LET beta emitting [131I]KX1 was lowest in BRCA1 mutant ovarian cancers SNU-251 and UWB1.289." (PMID 33352773, 2020). "BRCA1 and BRCA2 are the most known genes associated with hereditary breast and/or ovarian cancer (HBOC) risk." (PMID 32380732, 2020). "To date, no studies have applied a wholly unbiased WES-based approach to ovarian carcinoma predisposition gene discovery in a case cohort selected for HGSOC and enriched for hereditary cases where BRCA1 and BRCA2 involvement have been excluded." (PMID 32242007, 2020). "BRCA1 showed significant differences between ovarian cancer tissues and normal tissues in TCGA, Bonome and Yoshihara." (PMID 32762026, 2020). "A.iv The penetrance SG(t | c1), that is, the probability of developing disease by age t, is known for breast and ovarian cancer in BRCA1/2 carriers." (PMID 32226220, 2020). "BRCA1 has been traditionally studied in the context of breast and ovarian cancer, where it plays a pivotal role in establishing an adequate DNA damage response." (PMID 31940810, 2020). "The risks of developing ovarian cancer by age 80 years were 30% and 59% for BRCA1 carriers at the 5th and 95th percentiles of the PRSHGS distribution." (PMID 32665703, 2020). "We found 13 patients with the BRCA1 mutation and 13 patients with the BRCA2 mutation out of 274 ovarian cancer patients using the intersection between the mutation data and the immunity cluster data samples." (PMID 33282564, 2020).
ovarian carcinoma (continued). "All four patients who carried germline mutations in both BRCA1 and BRCA2 had a family history of breast/ovarian cancer." (PMID 32455662, 2020). "Background and objective: BRCA1 and BRCA2 are associated with many cancer types in addition to hereditary breast and ovarian cancers." (PMID 32349445, 2020). "Detection of mutations in the BRCA1 and BRCA2 genes from ovarian cancer is meaningful for both genetic counseling and treatment decision making with PARP inhibitors." (PMID 32856862, 2020). "Monoallelic mutations in five of these genes (BRCA1, BRCA2, PALB2, BRIP1 and RAD51C) increase the susceptibility to breast/ovarian cancer and are used in clinical diagnostics as bona-fide hereditary cancer genes." (PMID 32235514, 2020). "There were 23 patients with the BRCA1 mutation and 20 patients with the BRCA2 mutation out the 436 ovarian cancer patients sampled." (PMID 33282564, 2020). "Germline pathogenic variants in the tumour-suppressor genes, BRCA1 and BRCA2, predispose humans to breast and ovarian cancer with reduced effects on the risk of cancer in other tissues." (PMID 33081408, 2020). "Group 3 consists of comparison of miRNAs of BRCA1 positive ovarian cancer patient with all other BRCA1 positive healthy individuals." (PMID 32854743, 2020). "Cancers with a BRCA1 mutation, such as TNBC and ovarian cancer, are usually treated with PARP inhibitors as targeted drugs." (PMID 32570740, 2020). "The frequency of BRCA1 and BRCA2 germline variants in women with ovarian cancer varies in the literature (6–41%), with the lowest prevalence observed in unselected series of patients with OC." (PMID 32850417, 2020). "Most notably, patients with BRCA1/2 mutant ovarian cancer benefit from maintenance treatment with PARP inhibitors after (complete or partial) response to platinum-based chemotherapy." (PMID 32833070, 2020). "The NOVA trial showed that niraparib was effective in patients with platinum-sensitive ovarian cancer, demonstrating that PARP inhibitors are effective in carriers of mutations other than BRCA1 and BRCA2." (PMID 32679669, 2020). "The cumulative risks for ovarian cancer by age 70 years were estimated to be 59% for BRCA1 carriers and 17% for BRCA2 carriers, and germline BRCA1 and BRCA2 mutations were exclusively associated with high-grade serous histology." (PMID 32098383, 2020). "The majority of ovarian cancers that develop in BRCA carriers (either BRCA1 or BRCA2) are high-grade serous ovarian carcinomas (HGSOC)." (PMID 32341426, 2020). "In vitro experiments, two major bile acids, deoxycholic acid and chenodeoxycholic acid, were found to increase BRCA1 expression relative to untreated control OVCAR3 ovarian cancer cells, through interaction with bile acid receptors." (PMID 32381096, 2020). "BRCA1 is highly characterized as a tumor suppressor gene that was originally identified in hereditary breast and ovarian cancers." (PMID 33424604, 2020). "Our study is the largest comprehensive report of LGRs of BRCA1/2 in familial breast and ovarian cancer patients in the Middle and Eastern European region." (PMID 32629901, 2020). "Between 10% and 15% of women with EOC are genetically predisposed to ovarian cancer, and 90% have a BRCA mutation (BRCA1 or BRCA2)." (PMID 32679669, 2020). "Based on the best available evidence, variants in BRCA1, BRCA2, BRIP1, RAD51C, RAD51D, and the mismatch repair genes confer ovarian cancer risks that warrant the consideration of risk-reducing surgery." (PMID 33086730, 2020). "Previous studies on breast and ovarian carcinoma (BC and OC) revealed constitutional BRCA1 and RAD51C promoter hypermethylation as epigenetic alterations leading to tumor predisposition." (PMID 32276467, 2020). "In ovarian cancer, such mutations have been observed after progression on a PARP inhibitor for germline BRCA1, RAD51C and RAD51D mutations 11, 12, as well as in a case of somatic BRCA1 mutation." (PMID 31577852, 2020).
ovarian carcinoma (continued). "The “FoundationFocus CDx BRCA LOH” is designed to detect the presence of mutations in the BRCA1/2 genes and the percentage of the genome affected by LOH in DNA from tumor tissue samples of patients with ovarian cancer." (PMID 32455819, 2020). "For example, previous studies reported that the BRCA1 and BRCA2 genes, which are associated with increased risk of ovarian cancer, harbor mutations associated with platinum drug sensitivity and survival." (PMID 32404140, 2020). "In conclusion, this is the first study in Vietnam to use NGS to investigate mutations of BRCA1 and BRCA2 genes in ovarian cancer patients." (PMID 32856862, 2020). "The ovarian cancer prospective cohort comprised 3152 BRCA1 carriers with 108 incident cases and 2495 BRCA2 carriers with 56 incident cases." (PMID 32665703, 2020). "Secondly, the BRCA1 and BRCA2 mutation ratios in ovarian cancer were relatively low in the SNP data from TCGA." (PMID 33282564, 2020). "Identifying individuals with pathogenic variants in BRCA1 or BRCA2 is critical in the management and prevention of breast and ovarian cancer." (PMID 33081408, 2020). "BRCA1: The BRCA1 gene was analyzed because it is a common biomarker used to understand the efficacy of chemotherapeutic treatments in patients with breast and ovarian cancers." (PMID 33062421, 2020). "Breast cancer gene 1 (BRCA1)-associated RING domain protein 1 (BARD1) forms a heterodimer with BRCA1, a tumor suppressor associated with hereditary breast and ovarian cancer." (PMID 32722046, 2020). "For ovarian cancer, the PRS developed for predicting overall or HGS EOC demonstrated similar evidence of association with EOC risk, for both BRCA1 and BRCA2 carriers." (PMID 32665703, 2020). "Of all BRCA1 c.5266dupC carriers, 21 (63.6%) had been diagnosed withbreast and/or ovarian cancer at ages ranging from 22 and 63 years old (median = 43years)." (PMID 32453342, 2020). "The expression of BRCA1 in ovarian cancer tissues was lower than that in normal tissues; however, high levels of BRCA1 suggest a poor prognosis in ovarian cancer." (PMID 30636383, 2019). "A germline pathological variant in the BRCA1 or BRCA2 genes confers to a high lifetime risk of both breast and ovarian cancer, and when such a variant is confirmed, adequate strategies for surveillance can be recommended." (PMID 30136106, 2019). "In clear contrast, loss of BRCA1 or BRCA2 is apparently tolerated in breast and ovarian cancers affected by BRCA1 or BRCA2 mutations." (PMID 30626869, 2019). "Monoallelic mutations in five FA genes (BRCA1, BRCA2, PALB2, RAD51C, BRIP1) have now been confirmed to predispose to breast or ovarian cancer while biallelic mutations in these genes cause FA3." (PMID 31467304, 2019). "The opt-out referral process described in this study is s a feasible, effective, and patient-centred approach to increase access to BRCA1/2 testing for patients with ovarian cancer." (PMID 31061661, 2019). "In Italy, 5200 new ovarian cancers were diagnosed in 2018, highlighting an increasing need to test women for BRCA1/2." (PMID 31600986, 2019). "The aim of the present study is to evaluate the frequency of pathogenic and likely pathogenic variants in BRCA1 and BRCA2 among epithelial ovarian cancer Brazilian patients and compare clinical features of BRCA1/2 carriers and non-carriers." (PMID 30606148, 2019). "BRCA1- and BRCA2-deficient high-grade ovarian cancers (HGSOCs) were shown to have increased neoantigen burden, increased immune infiltrates, and higher PD-L1 and PD-1 expression compared to BRCA-proficient ovarian cancers." (PMID 31022191, 2019). "Female BRCA1 and BRCA2 mutation carriers have an increased lifetime risk of developing breast and/or ovarian cancer." (PMID 31370837, 2019).
ovarian carcinoma (continued). "BRCA1 carriers, in particular, were also more likely to be also diagnosed with an ovarian cancer themselves (ORBRCA1 vs non‐BRCA: 28.02 [10.72–73.29] and ORBRCA2 vs non‐BRCA: 8.11 [1.87–35.24]) than non‐BRCA patients (eTable 6 in Data Supplement 1)." (PMID 30175445, 2019). "Platinum-based chemotherapy has been proven to be an effective treatment for BRCA1 and BRCA2 mutated breast and ovarian cancers as these compounds generate DNA cross-links that cannot be easily resolved with an impaired homologous recombination (HR)." (PMID 30871108, 2019). "Monoallelic germline mutations in the BRCA1 and BRCA2 genes predispose carriers to a high incidence of breast and ovarian cancer." (PMID 31671674, 2019). "BRCA1 and BRCA2 spliceogenic variants are often associated with an elevated risk of breast and ovarian cancers." (PMID 30736279, 2019). "Germline mutations in the BRCA1 and BRCA2 genes predispose carriers to breast and ovarian cancer, and there remains a need to identify the specific genomic mechanisms by which cancer evolves in these patients." (PMID 31182087, 2019). "The contribution of BRCA1 and BRCA2 mutations to the incidence of breast and ovarian cancer has been acknowledged for a number of years." (PMID 30689103, 2019). "In the past, having a family history of breast and/or ovarian cancer was the main screening criteria for referral to genetic counselling for BRCA1/2 testing." (PMID 31061661, 2019). "This study aims at studying the aberrant promoter hypermethylation of two tumor suppressor genes, RASSF1a and BRCA1, known to be involved in ovarian carcinoma pathogenesis." (PMID 31653147, 2019). "Women carrying germline pathogenic mutations in BRCA1 and BRCA2 are at high risk of developing breast as well as ovarian cancer." (PMID 31225507, 2019). "Initially, the BRCA1 locus region was shown to be lost in sporadic cases of breast and ovarian cancers, prompting the investigation of a putative role of BRCA1 as a driver gene in sporadic cases of BC and OC." (PMID 31013702, 2019). "Mutations of BRCA1 and BRCA2 are associated with the risk of ovarian cancer at 50% and 20%, respectively." (PMID 30362670, 2019). "A high rate of germline BRCA1 and BRCA2 mutations was detected in our retrospective analysis of 392 families with pancreatic cancer associated with breast and/or ovarian cancer." (PMID 30736435, 2019). "BRCA1 methylation frequencies have been reported to be ranging from 10-89% in ovarian cancers (Prieske e3et al., 2017)." (PMID 31653147, 2019). "BRCA1 and BRCA2 germline mutations have been associated with approximately 25% of the familial cases of breast and ovarian cancer; therefore, BRCA1 and BRCA2 represent classical tumour suppressor genes." (PMID 31273933, 2019). "BRCA1 and BRCA2 are tumor suppressor genes in which mutations have been widely correlated with hereditary and sporadic breast and ovarian cancer." (PMID 31615159, 2019). "In patients diagnosed with ovarian cancer, 13 of 30 were 9–12 del BRCA1 carriers, which represents 43%." (PMID 31545835, 2019). "Once a diagnosis of BRCA1/2 related HBOC was made for an ovarian cancer patient, family members are assessed to search for the family specific high-risk gene variant." (PMID 31600986, 2019). "Transfection with let-7e sensitized ovarian cancer cells to cisplatin, down-regulated BRCA1 and Rad51 expression and repressed the repair of cisplatin-induced DNA double strand break." (PMID 35582723, 2019). "It is well-known that germline mutations in BRCA1 or BRCA2 genes increase risks of breast and ovarian cancer, as well as pancreatic cancer." (PMID 31877165, 2019). "Carriers of BRCA1 and BRCA2 pathogenic variants have a risk of developing ovarian cancer about 45 and 20% until 80 years old, respectively." (PMID 30606148, 2019).
ovarian carcinoma (continued). "Mutual exclusivity of BRCA1/2 mutation/deletion and CCNE1 amplification has been shown previously in ovarian cancers." (PMID 30665374, 2019). "Germ-line mutations in BRCA1 and BRCA2 tumor suppressor genes comprise most of the familial breast and ovarian cancer cases and significantly increase the chance of cancer development in carriers." (PMID 32042831, 2019). "Based on emerging data for the role of maintenance PARP inhibitor therapy in ovarian cancer patients whose tumors harbor BRCA1/2 defects, we treated him with PARP inhibitor maintenance after chemotherapy." (PMID 31565603, 2019). "In future experiments, we will continue to study the important role of BRCA1 in resistance regulation and dig deeper into the mechanisms of autophagy functions in ovarian cancer." (PMID 30636383, 2019). "Signature 3 is strongly associated with germline and somatic BRCA1 and BRCA2 mutations in breast, pancreatic, and ovarian cancers, which was previously reported in GGNs." (PMID 31058088, 2019). "Our study is the first report on aberrant hypermethylation of RASSF1A and BRCA1 in cell-free circulating DNA of epithelial ovarian cancer from the Asian population." (PMID 31653147, 2019). "One patient with BRCA1-mutated, platinum-refractory, PARP inhibitor–resistant ovarian cancer achieved partial response (PR) for 6 months." (PMID 31018854, 2019). "Germline pathogenic variants (PVs) in the BRCA1 and BRCA2 genes confer a significantly increased lifetime risk for the development of both breast and ovarian cancer." (PMID 31336956, 2019). "Germline BRCA1 and BRCA2 mutations are most common in high grade serous histologic type (high grade serous cancer – HGSC), the most frequent type of epithelial ovarian cancer, and appear in 16–39.2% of cases." (PMID 30940100, 2019). "Genetic testing for disease-causing mutations in BRCA1, BRCA2, PALB2, and other BC susceptibility genes is strongly recommended for people with a BC and/or ovarian cancer family history." (PMID 30940775, 2019). "About 10–15% of ovarian cancers are diagnosed in patients who have a hereditary breast and ovarian cancer (HBOC) syndrome because they are carriers of a BRCA1/2 pathogenic variant (PV)." (PMID 31600986, 2019). "Our mechanistic studies discovered that ZC3H18 and E2F4 depletion reduces BRCA1 levels in ovarian cancer cell lines and low-passage, short-term ex vivo-cultured HGSOC PDX models freshly isolated from mice." (PMID 31604914, 2019). "Subsets of breast and ovarian cancer have well studied DNA repair aberrations in homologous recombination proteins BRCA1/256." (PMID 31375789, 2019). "Germline pathogenic variants in BRCA1 and BRCA2 account for about 14% of all epithelial ovarian cancers and 16.6% of high-grade serous ovarian cancers." (PMID 31013702, 2019). "Their germline mutations and, consequently, loss of function were associated with the higher risk of breast (ranging from 57% in BRCA1 mutation to 45% in BRCA2 mutation) and ovarian cancers (ranging from 11% in BRCA1 mutation to 40% in BRCA2 mutation)." (PMID 31109041, 2019). "Both BRCA1 and BARD1 are tested on clinical gene panels for breast and ovarian cancer susceptibility." (PMID 30925164, 2019). "Targeted therapies offer an opportunity to change the course of ovarian cancer treatment; however, efficacy has been modest with the exception of PARPi in patients with abnormalities in BRCA1/2." (PMID 31191824, 2019). "Due to their role in BRCA1/BRCA2 DNA repair pathway, the loss-of-function mutations of RAD51C, RAD51D, BRIP1, and BARD1 genes have been generally considered as ovarian cancer susceptibility genes." (PMID 31366178, 2019). "The carriers of BRCA1 or BRCA2 gene mutations have very high lifetime risks for breast and ovarian cancers." (PMID 30622657, 2019). "Since ovarian cancers are characterized by complex and changing genetic profile, BRCA1/2 tumor testing results can potentially vary depending on disease stage and sample site." (PMID 30940100, 2019).